CP (ceruloplasmin)
Description:
Multifunctional blue, copper-binding (6-7 atoms per molecule) glycoprotein. It has ferroxidase activity oxidizing Fe(2+) to Fe(3+) without releasing radical oxygen species. It is involved in iron transport across the cell membrane. Copper ions provide a large number of enzymatic activites. Oxidizes highly toxic ferrous ions to the ferric state for further incorporation onto apo-transferrins, catalyzes Cu(+) oxidation and promotes the oxidation of biogenic amines such as norepinephrin and serotonin. Provides Cu(2+) ions for the ascorbate-mediated deaminase degradation of the heparan sulfate chains of GPC1 (By similarity). Has glutathione peroxidase-like activity, can remove both hydrogen peroxide and lipid hydroperoxide in the presence of thiols. Acts as an inhibitor of the peroxidase activity of MPO (By similarity). Also shows NO-oxidase and NO2 synthase activities that determine endocrine NO homeostasis.
Synonyms: AB073614; CP-2
Tractability: Small molecule: a structure with a bound ligand is known; it has a high-quality binding pocket. Antibody: UniProt places it where antibodies can reach, with high confidence; its Gene Ontology location is reachable by antibodies, with high confidence; UniProt predicts a signal peptide or a membrane-spanning region. PROTAC: ubiquitination databases record sites on it; its protein half-life has been measured.
Gene: Protein-coding gene on chromosome 3 (149,162,410 to 149,221,998, reverse strand). Ensembl gene ENSG00000047457.
Subcellular location: Secreted
Pathways (Reactome):
Disease: Defective CP causes aceruloplasminemia (ACERULOP); Defective SLC40A1 causes hemochromatosis 4 (HFE4) (macrophages)
Metabolism of proteins: Post-translational protein phosphorylation; Regulation of Insulin-like Growth Factor (IGF) transport and uptake by Insulin-like Growth Factor Binding Proteins (IGFBPs)
Transport of small molecules: Iron uptake and transport; Metal ion SLC transporters
Gene Ontology:
Molecular function: ferroxidase activity; glutathione peroxidase activity; oxidoreductase activity, acting on metal ions, oxygen as acceptor; phospholipid-hydroperoxide glutathione peroxidase activity; protein-folding chaperone binding; peroxidase inhibitor activity; copper ion binding; oxidoreductase activity; oxidoreductase activity, acting on metal ions
Biological process: intracellular copper ion homeostasis; intracellular iron ion homeostasis; cellular oxidant detoxification
Cellular component: blood microparticle; extracellular exosome; extracellular region; lysosomal membrane; endoplasmic reticulum lumen; plasma membrane
Genetic constraint (gnomAD): Loss-of-function variants: 59 observed, 117.37 expected, observed/expected ratio (o/e) 0.5, 90% interval 0.41 to 0.62. The upper end of that interval is the gene's LOEUF score, 0.62, which puts it in group 2 of 6, group 1 being the genes least tolerant of losing a copy. Missense variants: 1,135 observed, 1,293.2 expected, observed/expected ratio (o/e) 0.88, 90% interval 0.83 to 0.92. Synonymous variants: 427 observed, 440.57 expected, observed/expected ratio (o/e) 0.97, 90% interval 0.89 to 1.05.
Gene-disease validity (ClinGen):
ClinGen rates the evidence that CP causes each of these diseases.
aceruloplasminemia (autosomal recessive): Definitive. An adult-onset disorder of neurodegeneration with brain iron accumulation (NBIA) characterized by anemia, retinal degeneration, diabetes and various neurological symptoms.
Homologues: Orthologues: chimpanzee CP (99% identical), macaque CP (96% identical), pig CP (87% identical), rabbit CP (87% identical), dog CP (84% identical), guinea pig CP (83% identical), mouse Cp (83% identical), rat Cp (82% identical), tropical clawed frog cp (57% identical), zebrafish cp (55% identical). Paralogues in human: HEPHL1 (51% identical), HEPH (47% identical), F5 (34% identical), F8 (34% identical), CNTNAP3 (15% identical), CNTNAP3B (15% identical), CNTNAP4 (15% identical), CNTNAP5 (15% identical), CNTNAP2 (14% identical), CUBN (14% identical), NRXN2 (13% identical), CNTNAP1 (12% identical), and 23 more.
Diseases named in the same sentence as CP in open-access papers:
CP is named in the same sentence as 469 diseases in open-access papers, as found by Europe PMC text mining. Sharing a sentence is not in itself a finding about the gene and the disease. The quoted sentences say what the papers report.
aceruloplasminemia (68 papers, 2009 to 2026). "In aceruloplasminemia, a parkinsonism caused by loss of ceruloplasmin (an oxidase required for cellular iron export), iron accumulates in the basal ganglia, especially in astrocytes." (PMID 41480756, 2026). "Aceruloplasminemia (ACP) is a rare recessive disease caused by loss of ceruloplasmin activity due to pathogenic variants in the ceruloplasmin (CP) gene." (PMID 40043514, 2025). "Variants in the CP gene can lead to aceruloplasminemia, a rare genetic disorder characterised by iron accumulation in the brain and other organs which can result in neurological and systemic symptoms." (PMID 41442065, 2025). "WES analysis revealed a heterozygous pathogenic variant [c.1948G > A (p.Gly650Arg)] in the CP gene, related to autosomal recessive aceruloplasminemia." (PMID 40870862, 2025). "Aceruloplasminemia is a rare autosomal recessive, adult-onset disorder caused by mutations in the Ceruloplasmin (CP) gene." (PMID 39965404, 2025). "Aceruloplasminemia (ACP) is a rare genetic disorder that manifests in adulthood due to mutations in the CP (ceruloplasmin) gene, causing iron accumulation and neurodegeneration." (PMID 39165621, 2024). "Genetic loss of ceruloplasmin can lead to the autosomal recessive disorder “aceruloplasminemia”, which is characterized by progressive neurodegeneration." (PMID 38389896, 2024). "Disturbances in ceruloplasmin expression or function are associated with a number of diseases, including aceruloplasminemia, cirrhosis, and Parkinson’s disease." (PMID 39896931, 2024). "Of the proteins representing novel candidate PRTs, ceruloplasmin (CP), the most abundant plasma ferroxidase, stood out as a particularly interesting example because its deficiency characterizes aceruloplasminemia (ACP), an ultra-rare disease." (PMID 38291108, 2024). "We investigated iron/lipid dysmetabolism in the liver and adipose tissue of the ceruloplasmin-deficient mouse (CpKO) model of aceruloplasminemia and evaluated the effectiveness of ceruloplasmin replacement." (PMID 36674661, 2023). "In aceruloplasminemia and Friedreich’s ataxia, mutation in ferroxidase ceruloplasmin or in mitochondrial iron storage protein frataxin respectively can lead to iron overload in a multitude of organs." (PMID 35624729, 2022). "Mutation or knockout of the CP gene results in aceruloplasminemia, which is characterized by iron overload in the brain, leading to neurodegenerative diseases (NDs) with aging in humans and mice." (PMID 36443285, 2022). "Mutations in CP cause aceruloplasminemia, which results in iron accumulation and tissue damage and is associated with diabetes and neurologic abnormalities." (PMID 35501403, 2022). "Aceruloplasminemia due to mutations in the ceruloplasmin (CP) gene on chromosome 3 is characterized by iron accumulation not only in the brain, but also in other organs including liver and pancreas." (PMID 33935938, 2021). "Symptomatic aceruloplasminemia has also recently been described among heterozygous CP mutation carriers." (PMID 34401403, 2021). "Other considerations for low Cp levels are malabsorption, fulminant hepatic failure, or aceruloplasminemia caused by mutations in CP." (PMID 34572285, 2021). "Aceruloplasminemia is a late‐onset autosomal recessive disorder combining systemic and brain iron overload, caused by mutations in the ceruloplasmin (CP) gene." (PMID 34401403, 2021). "Mutations in the CP gene give rise to aceruloplasminemia, a rare neurodegenerative disease for which no cure is available." (PMID 34360993, 2021). "Accordingly, aceruloplasminemia, an autosomal recessive deficiency of ceruloplasmin caused by mutations in the ceruloplasmin gene, is associated with the accumulation of iron in the liver, pancreas, retina, and basal ganglia." (PMID 32013126, 2020). "Aceruloplasminemia is a rare AR disorder caused by mutations in the CP gene, which encodes for ceruloplasmin (Cp), a multicopper ferroxidase functioning as an iron exporter from cells." (PMID 33092153, 2020).
aceruloplasminemia (continued). "In this context Aceruloplasminemia (ACP) represents a paradigmatic disorder highlighting how the loss of CP function causes iron accumulation and neurodegeneration." (PMID 31024241, 2019). "Aceruloplasminemia is a rare, adult-onset, autosomal recessive disease caused by mutations in the CP gene, encoding CP." (PMID 31024241, 2019). "Aceruloplasminemia is a rare autosomal recessive disease resulting from mutations in the gene encoding ceruloplasmin." (PMID 30360383, 2018). "Aceruloplasminemia and atransferrinemia are rare disorders caused by deficiencies in ceruloplasmin or transferrin, respectively." (PMID 30420953, 2018). "Individuals with mutations in the CP gene (aceruloplasminemia) display significant iron deposition in the liver, glial cells, and, interestingly, in the pancreas." (PMID 29883959, 2018). "Aceruloplasminemia is a rare genetic disease caused by mutations in the ceruloplasmin (Cp) gene that result in protein loss or in a protein that has defective ferroxidase activity." (PMID 29183916, 2018). "Aceruloplasminemia is a monogenic disease caused by mutations in the ceruloplasmin gene that result in loss of protein ferroxidase activity." (PMID 29183916, 2018). "The importance of Cp in human iron homeostasis has been confirmed by the description of the human congenital disease, aceruloplasminemia, in which mutations in the ceruloplasmin gene lead to its absence in plasma." (PMID 26732058, 2015). "Hypoceruloplasminemia is a major risk factor for iron accumulation in WD, and evidence supports a critical role for ceruloplasmin in iron metabolism." (PMID 25915414, 2015). "Aceruloplasminemia is a rare genetic disorder caused by loss of function mutations in ceruloplasmin (CP)." (PMID 25011704, 2014). "Until now, only two genes coding for iron proteins have been identified as responsible of NBIA subtypes: the ceruloplasmin gene (CP) causing aceruloplasminemia and the L-ferritin gene (FTL) altered in neuroferritinopathy." (PMID 24847269, 2014). "Two forms are linked to mutations in genes directly involved in iron metabolism: neuroferritinopathy, associated to mutations in the FTL gene and aceruloplasminemia, where the ceruloplasmin gene product is defective." (PMID 24847269, 2014). "This is important since loss of ceruloplasmin function, as in aceruloplasminemia, often causes Parkinsonism in affected individuals." (PMID 24527451, 2014). "Aceruloplasminemia is a rare adult-onset autosomal recessive disease caused by mutations in the ceruloplasmin gene on chromosome 3q." (PMID 23825457, 2013). "The symptoms in aceruloplasminemia are caused by CNS iron accumulation due to defects in ceruloplasmin as described." (PMID 23055972, 2012). "Aceruloplasminemia is an autosomal recessive disorder of iron metabolism, caused by loss-of-function mutations in the gene encoding ceruloplasmin and with an adult-onset." (PMID 23055972, 2012). "A novel homozygous ceruloplasmin gene mutation, c.2554+1G>T, was identified as the cause of aceruloplasminemia in three affected siblings." (PMID 20801540, 2010). "Inflammation, hyperestrogenemia, or oral contraceptives are associated with increased ceruloplasmin levels and diseases such as aceruloplasminemia, protein-losing enteropathy, neurologic disorders such as cervical dystonia, other liver diseases, and copper deficiency will lower serum ceruloplasmin." (PMID 41427142, 2025). "CP activity is important in humans, since mutations that reduce CP production (as found in aceruloplasminemia or copper depletion), lead to iron accumulation in the brain, liver and pancreas indicating an inverse relationship between copper and iron in the liver." (PMID 40149659, 2025). "Importantly, mutations of the Ceruloplasmin (CP) gene cause a form of NBIA called Aceruloplasminemia, a very rare disorder with an estimated prevalence of one in two million." (PMID 39195264, 2024).
aceruloplasminemia (continued). "Another primary astrocytopathy linked to dysregulated iron homoeostasis is aceruloplasminemia, an autosomal recessive neurodegenerative disease caused by a loss of function mutations of the gene encoding ceruloplasmin, an enzyme that converts ferrous iron to ferric." (PMID 37828019, 2023). "Instead, a mutation in the CP gene, encoding for ceruloplasmin results in aceruloplasminemia." (PMID 36139084, 2022). "One that does is aceruloplasminemia, which is caused by mutations in ceruloplasmin (CP)." (PMID 35562883, 2022). "Interestingly, mutations in CP are associated with aceruloplasminemia in humans (OMIM604290) and mice leading to a decrease in iron export and an increase of iron retention in the liver." (PMID 33926013, 2021). "Aceruloplasminemia is caused by biallelic mutations in the CP gene, a 20 exons gene encompassing approximately 65 kb of DNA, located in chromosome locus 3q24-q25 and encoding CP." (PMID 31024241, 2019). "Aceruloplasminemia is an autosomal recessive disease caused by mutation in CP (CeruloPlasmin) gene." (PMID 25657764, 2014). "This phenotype is accelerated when either APP or CP is genetically ablated in mice and may be a contributory pathogenic mechanism in human diseases associated with each protein, such as Alzheimer’s disease, Parkinson’s disease or aceruloplasminemia." (PMID 25464026, 2014). "Notably, reduced ceruloplasmin can also be found in a variety of disorders other than WD, including liver failure, malnutrition, nephrotic syndrome, protein-losing enteropathy, malabsorption, acquired copper deficiency, glycosylation disorders, Menkes disease, and aceruloplasminemia." (PMID 40197188, 2025). "Background and Clinical Significance: Aceruloplasminemia (ACP), a member of the neurodegeneration with brain iron accumulation (NBIA) spectrum of disorders, is a rare disorder caused by mutations in the ceruloplasmin (CP) gene." (PMID 40729217, 2024). "Aceruloplasminemia (ACP) is a rare, autosomal recessive disorder caused by mutations in the ceruloplasmin (CP) gene." (PMID 40729217, 2024). "Due to ceruloplasmin’s ferroxidase activity, it is essential for iron (Fe) oxidation during cellular export, resulting in cellular Fe accumulation in aceruloplasminemia." (PMID 38389896, 2024). "On the other hand, serum CP levels are reduced in hepatic disorders, Wilson’s disease, aceruloplasminemia, and vitamin C overdose." (PMID 39337685, 2024). "Aceruloplasminemia is a deficit in functional ceruloplasmin, a protein that oxidizes Fe2+ into Fe3+, an essential step in incorporating iron into transferrin to transport iron to the bone marrow." (PMID 38355710, 2024). "The importance of CP in brain iron metabolism has been demonstrated in patients with the genetic disease aceruloplasminemia." (PMID 35918659, 2022). "Lifetime risks between 0.04 and 0.07 per 100,000 in all datasets were found for Kufor-Rakeb syndrome (KRS; MIM ID # 606693) and aceruloplasminemia (ACP; MIM ID # 604290) based on pathogenic variants in ATP13A2 and CP, respectively." (PMID 35180557, 2022). "CP was shown to be expressed predominantly in astrocytes and its lack thereof promoting astrocytic iron accumulation in aceruloplasminemia." (PMID 34292399, 2021). "Unsurprisingly, two other proteins involved in iron homeostasis, ceruloplasmin (ferroxidase activity) and ferritin (iron storage and trafficking), are linked to two classical NBIA diseases, aceruloplasminemia and neuroferritonopathy, respectively." (PMID 33263002, 2020). "FAHN (fatty acid hydroxylase-associated neurodegeneration; FA2H gene), NF (neuroferrinopathy; FTL gene), aceruloplasminemia (CP gene) and Woodhouse–Sakati syndrome (DCAF17 gene) are rare types." (PMID 33092153, 2020). "More than half of the patients with aceruloplasminemia (ACP), an autosomal recessive genetic disease caused by mutations in the gene encoding ceruloplasmin, have diabetes as their earliest symptom." (PMID 32817751, 2020).